BRCA1 (BRCA1 DNA repair associated)
Diseases named in the same sentence as BRCA1 in open-access papers (continued):
Sharing a sentence is not in itself a finding about the gene and the disease.
breast cancer (continued). "The most common pathogenic variant of the BRCA1 and BRCA2 in breast cancer patients was c.2635G > T and c.5164_5165del, respectively." (PMID 38167124, 2024). "The patterns are largely similar to those reported in women of European ancestry, except for age group 40–49 in BRCA1 PV carriers where the breast cancer RRs appeared to be lower compared to European studies (eTable 8)." (PMID 38333895, 2024). "As a comparison, we included the analysis of RAD51 foci in primary tumor samples from patients with untreated breast cancer with germline PVs in BRCA1, BRCA2, and PALB2, which showed a high prevalence of HRD (92.2% [95 of 103]), as expected." (PMID 38648056, 2024). "The breast cancer 1 and 2 (BRCA1/2) genes have a major role in the homologous recombination repair of DNA double-strand breaks occurring during the S phase." (PMID 39195440, 2024). "Smad3 interacts with BRCA1 in response to TGF-β stimulation and inhibits BRCA1-dependent DNA repair in MCF7 breast cancer cells (luminal type) by disrupting BRCA1 nuclear complexes." (PMID 38569937, 2024). "For example, another point mutation in OLA1 (E168Q) prevents it from forming a complex with BRCA1 and BARD1 and is associated with poor outcomes in breast cancer." (PMID 38889130, 2024). "Recently, poly adenosine diphosphate ribosyl (PARP) inhibitors have been incorporated and have shown significant outcome benefits in patients with pathogenic/likely pathogenic BRCA1/2 variants/mutations and high-risk HER2-negative breast cancer." (PMID 38338854, 2024). "Germline mutations in BRCA1 and BRCA2 (gBRCA1/2) are required for a PARP inhibitor therapy in patients with HER2-negative (HER2−) advanced breast cancer (aBC)." (PMID 39003306, 2024). "In the context of breast cancer in BRCA1/2 PV carriers, LSD-1 contributes to tumour development through various mechanisms." (PMID 39682099, 2024). "Demethylating agent 5-azacytidine can eliminate PARPi sensitivity in BRCA1-methylated breast cancer cell lines." (PMID 37588193, 2024). "Constitutional BRCA1 promoter methylation and MGMT promoter methylation have been shown to be associated with an increased risk of ovarian cancer and breast cancer." (PMID 38542081, 2024). "The intron-retained genes thus identified were also subjected to IPA, revealing that the shared pathways among them included “Hereditary Breast Cancer Signaling” and “Role of BRCA1 in DNA Damage Response”." (PMID 38789724, 2024). "Compared to the region bounded by position c.2282 to c.4071, carriers with BRCA1 PVs outside this region had breast cancer RRs between 1.4 and 1.5 and carriers with PVs in the upstream region (5′ to c.2830) had ovarian cancer RR of 1.3." (PMID 38333895, 2024). "As a direct comparison, we also performed a similar analysis for mammary tumors spontaneously developed in p18−/−;Brca1+/− mice." (PMID 38627785, 2024). "Even though rarer than BRCA1 and BRCA2, a short list of other highly penetrant genes are known to elevate breast cancer risk." (PMID 39402389, 2024). "Patients with a family history of breast cancer or personal history of ovarian cancer had higher rates of germline BRCA1/2 testing (41.4% and 57.9%, respectively)." (PMID 38254240, 2024). "Although, it is upregulated in breast cancer, There is also an increase in expression levels of miR-210 and BRCA1 mRNA in TNBC patients after treatment and with a worse prognosis." (PMID 38813102, 2024). "Peripheral blood samples were collected from 1556 patients diagnosed with BRCA1/2-negative early-onset breast cancer." (PMID 38914840, 2024). "Breast cancer cells harbouring BRCA1 PVs contribute to elevated levels of local oestrogen within the tumour microenvironment, leading to increased proliferation and growth of oestrogen-dependent tumours." (PMID 39682099, 2024). "There are higher rates of mastectomies as well as chemotherapy-only adjuvant and neoadjuvant regimes in BRCA1/2 PV-related breast cancers than in sporadic breast cancers." (PMID 39682099, 2024).
breast cancer (continued). "The present study aimed to detect the frequencies of inherited breast cancer caused by BRCA1 and BRCA2 genes among Kurdish breast cancer patients, including all the exome of these two genes, using next-generation sequencing (NGS)." (PMID 38863777, 2024). "The newly prepared M. oleifera leaves extract/Caffeine loaded chitosan nanoparticles showed potent anti-breast cancer effect through downregulating some of the widely known oncogenic genes (Her2, BRCA1 and BRCA2)." (PMID 39103402, 2024). "Our study therefore identifies FLT1 as a potential therapeutic target in PARPi-resistant, BRCA1/2-mutant breast cancer." (PMID 38956205, 2024). "Most videos created by hospitals and governments and breast cancer survivors were sent out around 2020, when health insurance coverage for BRCA1/2 genetic testing and HBOC treatment began in Japan." (PMID 37995024, 2024). "Breast cancer can eventually develop brain metastases in 40–50% of cases in HER2-positive BC and TNBC, and this risk can further increase in cases of BRCA1/2-mutated patients affected by TNBC." (PMID 39766062, 2024). "In this regard, scientists have discovered that BRCA1/2 (breast cancer types 1 and 2) are involved in DNA repair." (PMID 39001339, 2024). "BRCA1 and BRCA2 are tumor suppressor genes whose mutations have been historically associated with an increased lifetime risk of developing breast cancer (50 -80%) and ovarian cancer (30 - 50%)." (PMID 39314634, 2024). "Many genes, such as the tumor suppressor genes BRCA1 and BRCA2, have been found to be closely associated with the occurrence and development of breast cancer." (PMID 38244591, 2024). "While we highlight the BRCA1 status, there are other differences between these two breast cancer cell lines." (PMID 39409907, 2024). "Our findings suggested that functional LYN kinase was required for survival of BRCA1-null mammary tumour cells." (PMID 38149669, 2024). "Through reviewing relevant literature, we found that there was a lack of economic research on the use of Talazoparib in the treatment of BRCA1/2 mutant advanced breast cancer patients." (PMID 38886516, 2024). "Consistent with our previous observations, the WB and RT-qPCR results confirmed a significant increase in the expression of BRCA1 in breast cancer tissues compared to their adjacent counterparts." (PMID 38224491, 2024). "We compared the responses to olaparib (log2-fold change in cell abundance) with baseline gene expression data from 22 BRCA1/2 WT breast cancer cell lines using PRISM Repurposing screen data from the DepMap portal." (PMID 39062738, 2024). "The clinical treatment effect of Talazoparib group in BRCA1/2 mutant advanced breast cancer patients is better than that of the standard treatment group, and the progression free survival period is significantly prolonged." (PMID 38886516, 2024). "BRCA1 and BRCA2 are tumor suppressor genes that have been linked to inherited susceptibility of breast cancer." (PMID 39237557, 2024). "Local association study with Fisher’s test (Bonferroni-corrected significance threshold 0.05/8,268 = 6.05 × 10−6) was performed ‘re-discovering’ BRCA1 and BRCA2 as breast cancer susceptibility genes." (PMID 38200129, 2024). "ACC promotes breast cancer cell proliferation and survival and interacts with BRCA1, indicating links between fatty acid synthesis and the genetic factors involved in breast cancer susceptibility." (PMID 38610991, 2024). "Understanding their structures helps us grasp the intricacies of these regulatory interactions, contributing to our understanding of how disruptions in BRCA1-related pathways contribute to breast cancer." (PMID 38399423, 2024).
breast cancer (continued). "Another PARP inhibitor, veliparib, was tried in the BROCADE3 trial conducted in a similar patient population of P/LP BRCA1/2 with advanced HER2-negative breast cancer." (PMID 39507757, 2024). "BRCA1 and BRCA2 mutations account for about 40–50% of hereditary breast cancers and about 5–10% of all breast cancers." (PMID 38791944, 2024). "Most such families are explained by a mutation in either of the well-known breast-ovarian cancer genes BRCA1 and BRCA2, which account for approximately 10–15% of cases with familial risk of breast cancer." (PMID 38397208, 2024). "Mutation frequencies in different cohorts (HBOC, unselected breast cancer patient, benign breast disease patient, and normal control) from Asian countries on commonly tested HBOC related genes besides BRCA1/2." (PMID 39272924, 2024). "The results from both WB and RT-qPCR clearly demonstrated that the expression of BRCA1 in breast cancer cell lines was significantly upregulated when compared to normal breast epithelial cells." (PMID 38224491, 2024). "The BRCA1 and BRCA2 genes are key breast cancer risk factors, and they are involved in DNA damage repair, cell cycle control, apoptosis, and gene transcriptional regulation." (PMID 38711004, 2024). "In contrast, BRCA1 P/LP variant detection increased from 74% to 91%, and BRCA2 detection increased from 45% to 87% for current practice and testing of all breast cancers, respectively." (PMID 39766065, 2024). "BRCA1 and BRCA2 are high-penetrance breast cancer predisposition genes that were identified in the 1990s by genome-wide linkage analysis and positional cloning." (PMID 39438962, 2024). "A milestone in the molecular characterization of breast cancer was the discovery of the BRCA1 and BRCA2 genes." (PMID 39484719, 2024). "We took advantage of mammary tumor cell lines derived from p18−/−;Brca1MGKO mice, in which both Brca1 and Gata3 were undetectable." (PMID 38627785, 2024). "A genetic predisposition is observed in about 5–10% of breast cancers, and BRCA1 and BRCA2 are the most recognized mutations associated with a lifetime risk for breast cancer of 50–85% and 45–69%, respectively." (PMID 38656711, 2024). "The characteristics of breast cancers that develop in BRCA1 carriers, including higher rates of early onset, high-grade, and triple-negative disease, provide possible explanations in support of these real-world survival differences." (PMID 38248108, 2024). "Among these, mutations in the BRCA1 and BRCA2 genes have a particularly important role in the development of breast cancer." (PMID 39192282, 2024). "Some women were part of online support groups in the form of Facebook groups or website forums (e.g. Hysterectomy Sisters, BRCA1 BRCA2 Genetic Ovarian & Breast Cancer Gene)." (PMID 38698439, 2024). "Resveratrol is a phytoestrogen that binds to estrogen receptors and activates them, controlling the transcription of estrogen-responsive target genes including BRCA1 and BRCA2, which are connected to breast cancer risk." (PMID 38711004, 2024). "In BRCA1 pathogenic variant carriers, BRRM has proven to decrease breast cancer-specific and all-cause mortality." (PMID 38892081, 2024). "In a BRCA1-mutant intracranial metastatic breast cancer model, AZD9574 led to significant tumor regression and improvement in survival, in comparison to olaparib." (PMID 39201718, 2024).
breast cancer (continued). "While the fraction of breast cancers that are TNBC varies between 10% and 20% among ethnic groups, about 70% of breast cancer cases arising in women harboring a PV in BRCA1 are TNBCs." (PMID 40225940, 2024). "To summarize, mutations in BRCA1 and BRCA2 significantly increase breast cancer risk, and PARP inhibitors like olaparib and talazoparib have been effective in targeting these mutations." (PMID 38256428, 2024). "Hereditary breast cancer represents a significant proportion of breast cancer cases worldwide, and BRCA1 and BRCA2 explain the majority of these." (PMID 38893140, 2024). "There are however no ongoing trials investigating the interactions between LSD-1 and BRCA1/2 for hereditary breast cancer." (PMID 39682099, 2024). "Using new PARPi-resistance models of Brca1- and Bard1-mutant breast cancer generated in-vivo, we identified FLT1 (VEGFR1) as a driver of resistance." (PMID 38956205, 2024). "HRD positivity in HER2-positive breast cancer is primarily linked to BRCA2 deletion and BRCA1 promoter methylation." (PMID 39334297, 2024). "Approximately 55–72% of women carrying a harmful BRCA1 gene variant and around 45–69% of those with a harmful BRCA2 gene variant are expected to develop breast cancer during their 70-80 years of life." (PMID 38182557, 2024). "We observed an 80% reduction in breast cancer mortality for women with BRCA1 sequence variations after they entered an MRI surveillance program." (PMID 38421676, 2024). "ESR1, BRCA1, CTNNB1, and BAX was associated with breast cancer cells proliferation, we further employed Ki67 immunohistochemical staining to evaluate tumor cell proliferation." (PMID 39045563, 2024). "Breast cancer gene 1 (BRCA1) and BRCA2 are well-known mutations responsible for approximately half of the hereditary breast cancer and belong to the class of high-penetrance breast cancer susceptible genes." (PMID 38464382, 2024). "The American Society of Clinical Oncology (ASCO) recommends offering BRCA1/2 genetic testing to all patients newly diagnosed with breast cancer who are 65 years or younger." (PMID 39624521, 2024). "New biomarkers have been identified, such as poly ADP-ribose polymerase (PARP) inhibitors, which have proven to be effective in the breast cancer genes BRCA1/2 subgroup of patients." (PMID 39001339, 2024). "Testing was initially limited to BRCA1/2 genes only, but our understanding of breast cancer genetics has expanded dramatically." (PMID 39590369, 2024). "Our study showed that breast cancer RRs vary substantially by age, from approximately 25 for BRCA1 and 10 for BRCA2 at age <30 to 10 for BRCA1 and 5 for BRCA2 at age >70." (PMID 38333895, 2024). "In the MCF-7 breast cancer cell line, estrogen treatment stimulated increased BRCA1 protein expression." (PMID 39329990, 2024). "From the perspective of medical and health services in China and the United States, the Talazoparib group is more economical than the standard treatment group in treating patients with BRCA1/2 mutant advanced breast cancer." (PMID 38886516, 2024). "Most of the 28 patients who underwent quadrantectomy in combination with other surgical procedures corresponded to inherited breast cancer cases with PVs in associated genes (71.4%; 20/28), mainly BRCA2 (9/20; 45%) and BRCA1 (7/20; 35%)." (PMID 38893140, 2024). "BRCA1-hypermethylated breast cancers on average are diagnosed at a younger age compared to sporadic TNBC." (PMID 40225940, 2024).
breast cancer (continued). "This rationale is understandable, as most trials assessing the benefit of these procedures in patients with BRCA1–2 PVs excluded women with advanced breast cancer." (PMID 38893140, 2024). "The susceptibility genes BRCA1 (breast cancer 1) and BRCA2 (breast cancer 2) are critical in the DNA damage response (DDR)." (PMID 39272660, 2024). "Next, to identify BRCA1-downregulating compounds that cooperate with PARPi in breast cancer cells, the 35 candidate drugs were tested for their capacity to sensitize MDA-MB-231 cells to olaparib." (PMID 38993666, 2024). "Specifically, we investigated BRCA1-mutant cell lines in tandem with isogenic pairs in which wild-type BRCA1 was restored in an aggressive breast cancer model." (PMID 39730675, 2024). "Mutations in the BRCA1 and BRCA2 genes increase the risk of breast cancer, with cumulative risks of 72% for BRCA1 and 69% for BRCA2 mutation carriers." (PMID 38256428, 2024). "BRCA1 and BRCA2 are genes strongly linked to breast cancer, primarily due to their roles in DNA damage repair." (PMID 39598249, 2024). "Two of the BRCA1 carriers developed breast cancer (persons 025 and 056), one of whom was diagnosed at 34 years of age; the subtype was unavailable." (PMID 38063999, 2024). "Despite these recommendations, our data showed that all female BRCA1/2 carriers who underwent breast cancer surveillance used breast ultrasonography (n = 13), while only a small number (n = 4) used breast MRIs." (PMID 39590130, 2024). "In this context, genetically engineered mouse models (GEMMs) of BRCA1- and BRCA2-associated breast cancer have proven invaluable advantages." (PMID 38789420, 2024). "BRCA1 and BRCA2 genes are significant markers for increased breast cancer risk, with mutations in these genes associated with a higher likelihood of developing breast and ovarian cancers." (PMID 38516286, 2024). "USP4 positively regulates the stability and function of BRCA1 through de-ubiquitination, and plays important role in the suppression of breast cancer." (PMID 38734703, 2024). "It is strongly recommended that breast cancer patients with a family history, of bilateral cancer, HER2-, and Ki67 ≥ 15% undergo testing for mutations of the BRCA1/2 genes." (PMID 38167124, 2024). "In the Dutch HEBON cohort, death from breast cancer was seen in 2% of BRCA1 carriers electing for surveillance vs. 0.1% of BRCA1 carriers electing for bilateral RRM (HR 0.06, 95% CI 0.01–0.46)." (PMID 38248108, 2024). "The identification of mutations in the BRCA1 and BRCA2 genes, pivotal in HR repair of DSBs, was associated with a breast cancer risk as high as 70% and emphasized the importance of intact DDR in mitigating cancer risk." (PMID 40191738, 2024). "Its expression was higher in BRCA1-positive patients (P=0.0040), indicating its potential role in breast cancer progression." (PMID 39267845, 2024). "For example, Ashkenazi Jewish women have a higher prevalence of BRCA1 and BRCA2 mutations, which significantly increase their risk of developing breast cancer." (PMID 39507494, 2024). "Among the genes related to the occurrence and development of breast cancer, the BRCA1/2 gene is the earliest and most studied gene." (PMID 38886516, 2024). "In contrast, a subset of BRCA1-mutant breast cancers was reported to show increased NFκB activity correlating with a good prognosis." (PMID 38149669, 2024).